PTGS2 (prostaglandin-endoperoxide synthase 2)
Diseases named in the same sentence as PTGS2 in open-access papers (continued):
Sharing a sentence is not in itself a finding about the gene and the disease.
colorectal cancer (150 papers, 1999 to 2026). A primary or metastatic malignant neoplasm that affects the colon or rectum. "High PINK1 expression promotes proliferation and chemoresistance in non-small cell lung cancer, and upregulated PTGS2 expression is associated with increased risk of colorectal cancer and increased cell migration ability." (PMID 39951474, 2025). "HCA7 cells release the highest TXB2 levels at baseline, associated with the highest expression of PTGS2 than the other colorectal cancer cell types." (PMID 36672299, 2023). "Post-diagnosis regular aspirin use was associated with reduced colorectal cancer-specific and overall mortality, especially in patients with positive PTGS2 (COX-2) expression and mutated PIK3CA tumors, reported by a meta-analysis." (PMID 36545311, 2022). "COX2 overexpression has been associated with colorectal cancer progression and metastasis, it is upregulated in tumors vs. normal colon tissue and we have shown that PTGS2 (that encodes COX2) is also up-regulated in human xenografts in nude mice." (PMID 35153760, 2021). "Another study revealed that PTGS2 is a prognostic biomarker in colorectal cancer and correlated with high tumor recurrence risk and poorer specific survival." (PMID 34707562, 2021). "It is believed that the regular use of PTGS2 inhibitors, such as aspirin, can reduce the risk of colorectal cancer." (PMID 27764771, 2016). "Among 382 patients with PTGS2-positive colorectal cancer, the highest level of physical activity was associated with an 82% lower cancer–specific mortality compared with the least level." (PMID 27437765, 2016). "The association of PTGS2 polymorphism with colorectal cancer points towards the implication of inflammation as an important mediator in the carcinogenesis of these tumours." (PMID 15173859, 2004). "In conclusion, we have detected weak associations between several PTGS2 polymorphisms and risk of colorectal cancer, which reach statistical significance for polymorphism PTGS2.9850 (OR=2.49)." (PMID 15173859, 2004). "In this study, we have found an increased risk for colorectal cancer associated with polymorphisms in PTGS2, a gene triggered by the inflammatory response, and governing the synthesis of prostaglandins." (PMID 15173859, 2004). "In this study, we have explored the impact of polymorphisms in PTGS2 on risk of colorectal cancer as well as possible interactions between these polymorphisms and the use of NSAIDs." (PMID 15173859, 2004). "We explored the relationship between PTGS2 polymorphisms and exposure to NSAIDs, since these have been shown both to inhibit PTGS2 action in vitro and to protect from colorectal cancer." (PMID 15173859, 2004). "An association was detected between colorectal cancer and a polymorphism in the untranslated region of exon 10 of PTGS2, with an odds ratio (OR) of 2.49, 95% confidence interval (CI) of 1.17–5.32, P=0.01." (PMID 15173859, 2004). "This may be explained by effect modification of associations between the PTGS2 SNP and colorectal cancer risk by dietary factors that may differ between Danish and Norwegian populations as for example fish and fruit and vegetables." (PMID 25166592, 2014). "Furthermore, the presence of the G allele has been previously associated with higher transcriptional activity of PTGS2 in colorectal cell lines and the implication of this SNP in colorectal cancer susceptibility had already been reported by our group and in other Caucasian populations." (PMID 33440718, 2021). "Finally, we have investigated protection from colorectal cancer by NSAIDs and whether it might be modulated by PTGS2 polymorphisms." (PMID 15173859, 2004). "For example, the PTGS2 gene target is highly expressed in colorectal cancer, and is also highly expressed in colorectal cancer." (PMID 38666938, 2024). "PTGS2 was detected in 94% of colorectal cancers, and the expression was significantly enhanced vs. normal mucosa." (PMID 38495101, 2024).
colorectal cancer (continued). "We aimed to verify the impact of the interaction of platelet-derived mEVs of CRC patients and HS on PTGS2 expression in the four colorectal cancer cell lines." (PMID 36672299, 2023). "In colorectal cancer, HIF1A, MMP9, and PTGS2 had the highest mutation frequency at 5.8%, 7.7%, and 5.8%, respectively, while in melanoma, PPARG and TGFB1 had the highest mutation frequency at 4.7% and 1.9%, respectively." (PMID 37033970, 2023). "Mesenchymal stem cell-secreted PGE2 promoted the expansion of colorectal cancer stem cells and the formation of hepatic metastases, which administration of celecoxib, an inhibitor of prostaglandin-endoperoxide synthase 2, prominently restrained." (PMID 36494785, 2022). "It was reported that upregulation of PTGS2 induces the ferroptosis of colorectal cancer cells; thus, PTGS2 is considered as a marker of ferroptosis." (PMID 35359830, 2022). "ORAI1 also regulates EGF-mediated and lipopolysaccharide-mediated PTGS2 gene expression in colorectal cancer cell lines and AGS gastric adenocarcinoma cells, respectively." (PMID 35682546, 2022). "PTGS2 is required in diseases, such as colorectal cancer, while MMP2 mostly plays a role in inflammatory responses and immune responses." (PMID 35227278, 2022). "We revealed that quercetin, stigmasterol, kaempferol, baicalein, and acacetin played a critical role in colorectal cancer by affecting PTGS2, NR3C2, CA2, and MMP1." (PMID 34125845, 2021). "And many studies reported that miR-212-5p directly targets SIRT2 and prostaglandin endoperoxide synthase-2 to suppress the proliferation of colorectal cancer cells and protect against ferroptosis-mediated neuronal death." (PMID 34666830, 2021). "Real time PCR was used to assess the expression levels of EGFR, HER-2 and PTGS-2 genes, as onco-markers in colorectal cancer." (PMID 32401801, 2020). "Some biomarkers can be used to predict the survival benefit of aspirin in colorectal cancer, including PTGS2 (COX-2) expression and the effects of the PIK3CA gene." (PMID 32646396, 2020). "The pleiotropic activities of the PGE2/PTGS2 pathway and their effect on cancer progression have been reviewed and explored throughout the years, particularly in colorectal cancer." (PMID 33081378, 2020). "Chronic inflammatory reaction in colorectal cancer is due to overexpression of PTGS2 by Streptococcus gallolyticus member bacteria (SGMB), which is believed to disrupt normal gut microbiota." (PMID 32380712, 2020). "The close interplay among these mediators is demonstrated by the up-regulation of CXCL5 and CXCL8 expression in human non-small cell lung cancer cells and of CXCL1 in colorectal cancer cells induced by PTGS2." (PMID 31920649, 2019). "Our result provides the clinical significance of miR-137 in the early stage of colorectal cancer development by directly inhibiting Aurora-A and PTGS2 expression." (PMID 27764771, 2016). "The expression pattern of miR-137 and Aurora-A or PTGS2 is negatively correlated in human colorectal cancer tissues and colon polyps." (PMID 27764771, 2016). "The expression of miR-137 and Aurora-A or PTGS2 was negatively correlated in both human colorectal cancer tissues and colon polyps." (PMID 27764771, 2016). "By Q-PCR and ROC analysis, we found that the expression of PTGS2 is negatively correlated with miR-137 in human colorectal cancer tissues and polyps, as well as acts as a biomarker that can predict the tendency toward to CRC formation." (PMID 27764771, 2016). "All these in silico findings strongly support the coordinated involvement of the PTGS2-PTGES axis in colorectal cancer development." (PMID 26498686, 2015). "In conclusion, this study suggests that increased PTGS2 mRNA level is an early event in colorectal cancer carcinogenesis." (PMID 25166592, 2014). "High intestinal PTGS2 mRNA level is an early event in colorectal cancer development as it occurs already in mild/moderate dysplasia." (PMID 25166592, 2014).
colorectal cancer (continued). "PTGS2 is a major inflammatory mediator up-regulated in several cancers, most notably colorectal carcinoma." (PMID 24848801, 2014). "The polymorphism rs20417 of the PTGS2 gene encoding COX-2 has been associated with an increased risk of rectal cancer in case of chronic NSAID use in a population-based study of more than 3,000 colorectal cancer patients and healthy individuals in the USA." (PMID 35222013, 2021). "Moreover, genetic variants in the genes encoding the four proteins (PTGS2, ABCC4, SLCO2A1, and HPGD, respectively) have been previously characterized in our population in colorectal cancer susceptibility and clinical outcome." (PMID 33440718, 2021). "Observational/retrospective studies indicate that prostaglandin-endoperoxide synthase-2 (PTGS2) inhibitors could positively affect colorectal cancer (CRC) patients’ survival after diagnosis." (PMID 32168749, 2020). "PIK3CA mutations (or PIK3CA amplifications) may result in constitutive activation of PI3K and the downstream AKT pathway, enhancing PTGS2 activity and prostaglandin E2 synthesis and leading to inhibition of apoptosis in colorectal cancer cells." (PMID 29152088, 2017). "Furthermore, the PTGS2 mRNA levels were increased both in normal and affected tissue from colorectal cancer patients compared to tissue from healthy control individuals." (PMID 25166592, 2014). "Indeed, a protective effect of PTGS2 inhibition has been shown for certain cancers, such as colorectal cancer." (PMID 24848801, 2014). "Additionally, aspirin, a modulator of PTGS2, has long been recognized for its chemopreventive effect in the setting of colorectal cancers and was recently demonstrated to reduce the development of colonic adenomas after F. nucleatum inoculation in the Apcmin/+ mouse model." (PMID 34700376, 2021). "However, the role of PTGS2 in gastric cancer may differ from its role in colorectal cancer." (PMID 38675376, 2024). "We found that our highest-ranked predicted targets were significantly enriched in targets with FDA-approved therapeutics for colorectal cancer (p-value < 0.025) that included EGFR, VEGFA, and PTGS2." (PMID 37790614, 2023). "A tumor-supporting role has also been suggested for Prostaglandin-Endoperoxide Synthase 2 (PTGS2) in HCC and colorectal cancer, which plays a critical role in the PI3K/AKT signaling pathway." (PMID 33292207, 2020). "Also the present study and previous meta-analyses suggest that the genotypes at PTGS2 A-1195G and T8473C but not G-765C are associated with altered risk of colorectal cancer, although we were unable to demonstrate association to altered levels of PTGS2 mRNA levels for any of the three SNPs." (PMID 25166592, 2014). "In this review, we highlight major advances in our understanding of the roles of PTGS2 and EGF signaling in colorectal cancer." (PMID 24213116, 2011). "Epidemiological, clinical, and animal studies have demonstrated that prostaglandin-endoperoxide synthase 2 (PTGS2) and epithelial growth factor (EGF) signaling pathways play key roles in promoting colorectal cancer growth and metastasis." (PMID 24213116, 2011). "The Prostaglandin-endoperoxide synthase 2 (Ptgs2) was slightly stimulated by EcN, yet not by CEC15, which has been associated with the development of colorectal cancer." (PMID 38008714, 2023). "Moreover, PTGS2 overexpression is an early event in colorectal cancer development, and PTGER2 plays a critical role in PTGS2-induced colon cancer development in an experimental system." (PMID 37601099, 2023). "In colorectal cancer, TFF3 promotes proliferation, invasion, and migration by enhancing CD147–CD44 interaction to activate transcription 3 (STAT3) and prostaglandin G/H synthase 2 (PTGS2) expression." (PMID 35626334, 2022).
colorectal cancer (continued). "Regarding the overall survival of colorectal cancer, two studies involving 4328 patients compared aspirin users with non-aspirin users among patients with weak PTGS2 (COX-2) expression." (PMID 32646396, 2020). "Two studies involving 560 patients compared overall survival in colorectal cancer among aspirin users compared with non-aspirin users in patients with strong PTGS2 (COX-2) expression." (PMID 32646396, 2020). "Expression of Aurora-A was gradually increased in colon polyps and colorectal cancer; not surprisingly, the expression level of PTGS2 mRNA is no different in colon polyps and colorectal tumorous tissues." (PMID 27764771, 2016). "PTGS2 SNPs that have been associated with altered PTGS2 mRNA levels/COX-2 activity in some studies, although not the present study, were associated with colorectal cancer risk." (PMID 25166592, 2014). "In addition, Tanshinone IIA has been found to promote ferroptosis in cutaneous melanoma via STAT1-mediated upregulation of prostaglandin-endoperoxide synthase 2 (PTGS2) expression and in colorectal cancer (CRC) through the suppression of SLC7A11 expression via the PI3K/AKT/mTOR pathway." (PMID 41502519, 2025). "Relevant research has reported that PTGS2-driven inflammatory responses can induce tumor expression of microRNA-21, which can increase the level of the inflammatory mediator prostaglandin E2 (PGE2) by down-regulating PGE2-metabolizing enzymes, contributing to colorectal cancer development." (PMID 36419007, 2022). "According to the subgroup analysis in our study, the effects of aspirin use on PIK3CA gene mutation and survival of patients with high expression of PTGS2 (COX-2) was different from that of patients with wildtype PIK3CA and PTGS2 (COX-2)-negative colorectal cancer." (PMID 32646396, 2020). "PTGS2 polymorphisms that have been associated with altered PTGS2 mRNA levels/COX-2 activity in some studies, although not the present study, were associated with colorectal cancer risk." (PMID 25166592, 2014).
colon carcinoma (122 papers, 2002 to 2025). "Expression levels of β-catenin target genes and proteins relevant to colon neoplasia, including c-Myc and Ptgs2, were reduced in colon tumors from βPix-deficient conditional knockout mice." (PMID 37805544, 2023). "βPix knockdown attenuated M3R agonist-induced human colon cancer cell proliferation, migration, invasion, and expression of PTGS2, the gene encoding cyclooxygenase-2, a key player in colon neoplasia." (PMID 37805544, 2023). "Genes containing variants uniquely associated only with sub-site risk plus raw P-values < 0.01 comprised rs12124257 in PTGS2 for colon cancer and 4 SNPs in IL10 for rectal cancer." (PMID 31027226, 2019). "Lastly, we sought an association between ARHGEF7 and PTGS2 expression in colon cancer." (PMID 37805544, 2023). "PTGS2 (COX2) upregulation is associated with F. nucleatum abundance in colon tumors." (PMID 34700376, 2021). "Studies have shown that TFs can reduce the expression of PTGS2 in the brain tissue of rats with cerebral ischemia and in the serum of patients with colon cancer, and DNJ can reduce the expression of PTGS2 in cancer cells, which is similar to our results." (PMID 41515216, 2025). "MES exposure in colon cancer cells resulted in changes in the expression of 56 ferroptosis-related genes, including ferroptosis markers such as PTGS2 and CHAC1." (PMID 39857803, 2025). "To gain additional mechanistic insights, we examined the effects of βPix deficiency on several genes associated with colon cancer progression; c-MYC, CCND1, and PTGS2, which encode c-Myc, β-catenin, and cyclooxygenase-2." (PMID 37805544, 2023). "It has been suggested that tumor recurrence and prognosis of colon tumor is related to PTGS2 expression." (PMID 35341150, 2022). "We sought to investigate the mRNA levels of Ptgs2 in our mouse model of colon cancer, CT26 cells-Balb/c mice, as well as those of the group of COX2 effector genes we identified in human colon cancer." (PMID 35153760, 2021). "The current study didn’t observe evidence of interaction between variant alleles of SNPs in previously reported genes- ALOX15, IL16, MDR1, NFkB, PTGS1 and PTGS2- with aspirin only use and CRC or colon cancer risk." (PMID 29425227, 2018). "We show that restrained colonic tumor growth and collateral tissue damage in MDR1A deficiency were associated with marked gene suppression of PTGS2 within intestinal tumors." (PMID 28686677, 2017). "This signaling provides a molecular explanation to PTGS2 and PTGES association and contribute to colon cancer advance, pointing out novel potential therapeutic targets in this oncological context." (PMID 26498686, 2015). "PPAR activity is also closely linked to the eicosanoid pathway of inflammation and PPARα induces cyclo-oxygenase-2 (PTGS2) expression, which is linked to the development of colon cancer." (PMID 16569247, 2006). "In human colon cancer cells, we observed that βPix knockdown reduced PTGS2 expression." (PMID 37805544, 2023). "Transcriptomic analysis of human colon tumors with high fusobacterial RNA levels revealed the Fusobacterium‐induced genes, PTGS2 (COX‐2), IL1β, IL6, IL8, and TNF (TNF‐α), indicating an NF‐κB‐driven proinflammatory response associated with colorectal carcinogenesis." (PMID 35244982, 2022). "Moreover, the interaction between miR-101-3p and PTGS2 has also been demonstrated in colon cancer, gastric cancer and esophageal squamous cell carcinoma but not in bone remodeling." (PMID 36425065, 2022). "The elevation of PTGS2 predicts poor prognosis in colon cancer." (PMID 33294000, 2020). "Moreover, S. gallolyticus proteins are contributed to the overexpress of cyclo-oxygenase-2 (Ptgs2) which is often increased in the colon cancer and prevents apoptosis and promotes angiogenesis in an in vitro condition." (PMID 29213996, 2017). "Gene expression of GABRB3, GABRG2, and GAD1 positively correlated with genes involved in the synthesis of PGE2 (PTGS2 and PTGES) as well as IL‐6 in human colon cancer." (PMID 38886975, 2024).